BHLHE22 (basic helix-loop-helix family member e22)
Description:
Inhibits DNA binding of TCF3/E47 homodimers and TCF3 (E47)/NEUROD1 heterodimers and acts as a strong repressor of Neurod1 and Myod-responsive genes, probably by heterodimerization with class a basic helix-loop-helix factors. Despite the presence of an intact basic domain, does not bind to DNA (By similarity). In the brain, may function as an area-specific transcription factor that regulates the postmitotic acquisition of area identities and elucidate the genetic hierarchy between progenitors and postmitotic neurons driving neocortical arealization. May be required for the survival of a specific population of inhibitory neurons in the superficial laminae of the spinal cord dorsal horn that may regulate pruritis. Seems to play a crucial role in the retinogenesis, in the specification of amacrine and bipolar subtypes. Forms with PRDM8 a transcriptional repressor complex controlling genes involved in neural development and neuronal differentiation.
Synonyms: bHLHb5; TNRC20; CAGL85; Beta3; Beta3a
Tractability: PROTAC: its protein half-life has been measured.
Gene: Protein-coding gene on chromosome 8 (64,580,365 to 64,583,627, forward strand). Ensembl gene ENSG00000180828.
Subcellular location: Nucleus
Subcellular location (Human Protein Atlas): Nuclear speckles; Nucleoplasm; Centrosome; Cytosol
Pathways (Reactome):
Cell-Cell communication: Regulation of CDH11 gene transcription
Gene Ontology:
Molecular function: sequence-specific double-stranded DNA binding; DNA-binding transcription factor activity, RNA polymerase II-specific; E-box binding; protein dimerization activity
Biological process: axon development; positive regulation of transcription by RNA polymerase II; sensory organ development
Cellular component: chromatin; nucleus
Genetic constraint (gnomAD): Loss-of-function variants: 8 observed, 11 expected, observed/expected ratio (o/e) 0.73, 90% interval 0.43 to 1.31. The synonymous counts are far from expectation, so gnomAD's model fits this gene poorly and the ratio says little. Missense variants: 570 observed, 432.02 expected, observed/expected ratio (o/e) 1.32, 90% interval 1.23 to 1.41. Synonymous variants: 353 observed, 219.57 expected, observed/expected ratio (o/e) 1.61, 90% interval 1.47 to 1.76.
Homologues: Orthologues: macaque BHLHE22 (97% identical), dog BHLHE22 (93% identical), pig BHLHE22 (91% identical), rabbit BHLHE22 (87% identical), mouse Bhlhe22 (86% identical), rat Bhlhe22 (86% identical), guinea pig BHLHE22 (72% identical), tropical clawed frog bhlhe22 (55% identical), zebrafish bhlhe22 (50% identical), Caenorhabditis elegans ngn-1 (11% identical), Drosophila melanogaster tap (10% identical), Drosophila melanogaster amos (10% identical), and 2 more. Paralogues in human: BHLHE23 (32% identical), OLIG2 (25% identical), OLIG3 (22% identical), OLIG1 (18% identical), NEUROD2 (16% identical), NEUROD1 (15% identical), NEUROD6 (14% identical), ATOH1 (14% identical), NEUROD4 (14% identical), NEUROG2 (11% identical), NEUROG3 (11% identical), ATOH8 (11% identical), and 3 more.
Diseases named in the same sentence as BHLHE22 in open-access papers:
BHLHE22 is named in the same sentence as 21 diseases in open-access papers, as found by Europe PMC text mining. Sharing a sentence is not in itself a finding about the gene and the disease. The quoted sentences say what the papers report.
endometrial cancer (6 papers, 2019 to 2025). Primary or metastatic malignant neoplasm involving the endometrium (mucous membrane that lines the endometrial cavity). "In humans, Bhlhe22 has been identified as a highly methylated gene in endometrial cancer with potential epigenetic biomarkers in cervical scrapings, while Bhlhe23 has been linked to mammalian retinal development." (PMID 34306008, 2021). "The sensitivity and specificity in endometrial cancer detection for BHLHE22/CDO1 were 84.8% and 88.0%, respectively." (PMID 31779688, 2019). "In other cancer types, SPON1 promotes the metastasis of human osteosarcoma, while methylated BHLHE22/CDO1/CELF4 panel could be used for endometrial cancer screening." (PMID 33860722, 2021). "EMPap integrated the methylation levels of BHLHE22 and CDO1 measured via qMSP along with age and BMI using a logistic regression model to calculate the endometrial cancer methylation (EM) score for EC identification." (PMID 39487683, 2024). "EMPap incorporated the methylation status of BHLHE22 and CDO1, along with age and body mass index (BMI), into a logistic regression model to calculate the endometrial cancer methylation (EM) score for identifying EC in cervical scrapings." (PMID 39487683, 2024). "We tested the effectiveness of the methylation status of four genes (BHLHE22, CDO1, TBX5, and HAND2) in endometrial cancer detection." (PMID 31779688, 2019). "Utilizing cervical scrapings as a potential genetic material, coupled with the use of DNA hypermethylation in specific genes, including CDO1, CELF4, BHLHE22, POU4F3, MAGI2, CADM1, MAL, miR124-2, ZSCAN12, and GYPC, has been investigated for endometrial cancer detection." (PMID 41008854, 2025).
breast carcinoma (2 papers, 2019 to 2022). "A recent breast cancer study reported that BHLHE22 is a signature gene, not only related to survival but closely associated with immunological responses." (PMID 35806162, 2022). "Of the genes evaluated, BHLHE22 was the most commonly modified in breast cancer (6.9% of the cases)." (PMID 30922380, 2019).
itch (2 papers, 2016 to 2020). "In our previous studies, we provided behavioral evidence that a subset of Bhlhe22-Cre neurons contribute to the inhibition of itch by counter-stimuli." (PMID 27991851, 2016).
prostate carcinoma (2 papers, 2023 to 2025). A carcinoma that arises from epithelial cells of the prostate gland. "In the context of prostate cancer, BHLHE22 and PRMT5 assemble a transcriptional complex that initiates CSF2 transcription, which then attracts many immunosuppressive neutrophils and monocytes, promoting the tumor’s metastasis to the bones." (PMID 40242775, 2025). "Studies on prostate cancer bone metastasis have identified BHLHE22 as a key transcription factor that is highly expressed in tumor cells." (PMID 40242775, 2025). "The findings of the study revealed that in bone metastatic prostate cancer, there is an increased expression of a gene called BHLHE22, which contributes to the establishment of an immunosuppressive bone tumor microenvironment (TME)." (PMID 38260135, 2023). "They investigated the role of a specific protein called BHLHE22 in prostate cancer bone metastasis and immunosuppressive bone TME." (PMID 38260135, 2023).
schizophrenia (2 papers, 2022 to 2024). A major psychotic disorder characterized by abnormalities in the perception or expression of reality. "Thus the enhanced risk for schizophrenia associated with BHLHE22 could be related to the influence or interaction with TCF4, and its downstream targets." (PMID 34664540, 2022). "There was a highly significant set=level association with schizophrenia (P = 6.31 × 10−9), with 21 genes individually associated at P < 0.05 including BHLHE22 but not SLIT1 or SLIT2." (PMID 39133845, 2024).
asthma (1 paper, 2020). "In addition, BHLHE22 and HMGN2, which contain bHLH and HMG-box protein domains, have been found to be highly associated with severe and moderate-to-severe asthma, respectively." (PMID 32512817, 2020).
depression (1 paper, 2022). "The gene BHLHE22 shows compelling genetic evidence of directly impacting the severe depression phenotype." (PMID 34664540, 2022). "We found that the developmental transcription factor BHLHE22 was significantly enriched for rare variation among individuals with severe depression (SKATO P = 0.000123, PAdjusted = 0.027)." (PMID 34664540, 2022). "One non-silent variant, (rs13279074) BHLHE22, was significantly associated with severe depression (Fisher’s Exact P = 6.98 × 10−05, PAdjusted = 0.038)." (PMID 34664540, 2022). "Additionally, BHLHE22 forms a repressor complex with the PRDM8 protein, whose protein-protein interaction site is not yet understood and may overlap with this association with severe depression." (PMID 34664540, 2022). "The primary finding in this paper links severe depression, a phenotype previously found to carry the high heritability of disease, to a rare non-silent change in the neuronal transcription factor BHLHE22." (PMID 34664540, 2022).
hearing loss (1 paper, 2020). "Therefore, the identification of BHLHE22 variants in additional affected individuals or mice models will be useful to understand the role of this gene, if any, in hearing loss." (PMID 32681043, 2020).
Hyperglycemia (1 paper, 2014). An increased concentration of glucose in the blood. "Integrating miR-182 tissue expression profile, target genes, and copy number in blood reveals that miR-182 plays a key role in crucial genes modulation, such as FOXO1 and BHLHE22, which leads to potential hyperglycemia and modulates the insulin secretion." (PMID 25530976, 2014).
neuropathies (1 paper, 2022). "BHLHE22 is a member of intronless genes, which are essential modulators of regulatory processes and have been proposed to be not only related to neuro-specific function but also to cancer, neuropathies, and developmental diseases." (PMID 35806162, 2022).
skin cancer (1 paper, 2022). "In addition, downregulation of BHLHE22 was observed in different tissues, including brain, lung, breast, cervix uteri, colon, and skin cancer using TCGA and GTEx databases, implying a universal role of BHLHE22 in cancer biology." (PMID 35806162, 2022).
Stroke (1 paper, 2023). Sudden impairment of blood flow to a part of the brain due to occlusion or rupture of an artery to the brain. "BHLHE22, downregulated in the stroke cohort, codifies for a protein belonging to the family of basic helix-loop-helix (bHLH) containing transcription factors." (PMID 37508918, 2023).
tumor (4 papers, 2016 to 2025). "Among them, neuronal growth regulator 1 (NEGR1) and basic helix-loop-helix family member e22 (BHLHE22) are crucial transcription factors associated with neuron development, which as tumor suppressors were downregulated in the subtype 1 of ESCC." (PMID 27966444, 2016). "Altogether, these data suggest that BHLHE22 expression increased proinflammatory leukocyte infiltration by upregulating expression of chemokines, resulting in a hot tumor microenvironment." (PMID 35806162, 2022). "Expression levels of seven CBX7 targets, namely Wnt10a, Ccne1, Fgfr2, Bhlhe22, Klhdc8a, Pde10a, and Dusp4, which had been significantly inhibited in miR-181ab1 KO compared to WT tumours in mice, were also significantly lower in either iClust2 or iClust3 than iClust1 HCCs." (PMID 35867177, 2022). "We further investigated tumor-infiltrating immune cells related to BHLHE22 expression in the UCEC TCGA database using TIMER and EPIC, which could predict and estimate the abundance value of tumor-infiltrating immune cells (TIICs) from the gene expression profile." (PMID 35806162, 2022).
cancer (3 papers, 2021 to 2022). A tumor composed of atypical neoplastic, often pleomorphic cells that invade other tissues. "Other IGs discussed in this study and linked with cancer and neurodevelopmental disorders were Pou3f3, bHLHE22, ASCL5, and Hist2h2be." (PMID 34306008, 2021). "Herein, we analyzed BHLHE22 expression in 54 paired cancer and normal endometrial tissue samples, and confirmed with databases (TCGA, GTEx, and human protein atlas)." (PMID 35806162, 2022). "However, the investigation of BHLHE22 function in clinical outcomes of cancer has been limited." (PMID 35806162, 2022).
psychiatric disease (1 paper, 2022). "This evidence suggests the mechanism of BHLHE22 in causing psychiatric disease is through transcriptional regulation via partner genes which alters neuronal architecture." (PMID 34664540, 2022). "However, multiple lines of evidence relate the BHLHE22 gene to psychiatric disease." (PMID 34664540, 2022).
BHLHE22 also shares sentences with these, for which no sentence is quoted: alcohol dependence (1 paper); bone metastasis (1); dyslexia (1); lung carcinoma (1); neurodevelopmental disorder (1); osteosarcoma (1).